RIMBP3B (RIMS binding protein 3B)
Description:
Probable component of the manchette, a microtubule-based structure which plays a key role in sperm head morphogenesis during late stages of sperm development.
Synonyms: RIM-BP3.B; RIM-BP3.2; RIMBP3.2
Tractability: PROTAC: ubiquitination databases record sites on it.
Gene: Protein-coding gene on chromosome 22 (21,383,751 to 21,389,478, forward strand). Ensembl gene ENSG00000274600.
Subcellular location: Cytoplasm, cytoskeleton
Subcellular location (Human Protein Atlas): Plasma membrane; Vesicles
Gene Ontology:
Molecular function: benzodiazepine receptor binding
Biological process: fertilization; neuromuscular synaptic transmission; spermatid development
Cellular component: manchette; nucleus; cytoskeleton
Genetic constraint (gnomAD): Loss-of-function variants: 0 observed, 0.95 expected, observed/expected ratio (o/e) 0, 90% interval 0 to 1.74. That is too few expected variants to judge how well the gene tolerates losing a copy. Missense variants: 0 observed, 33.26 expected, observed/expected ratio (o/e) 0, 90% interval 0 to 0.09. Synonymous variants: 0 observed, 10.52 expected, observed/expected ratio (o/e) 0, 90% interval 0 to 0.28.
Homologues: Orthologues: rat Rimbp3 (64% identical), mouse Rimbp3 (63% identical), Drosophila melanogaster Rbp (14% identical), Caenorhabditis elegans rimb-1 (14% identical). Paralogues in human: RIMBP3C (99% identical), RIMBP3 (99% identical), TSPOAP1 (29% identical), RIMBP2 (17% identical).
Diseases named in the same sentence as RIMBP3B in open-access papers:
RIMBP3B is named in the same sentence as 1 disease in open-access papers, as found by Europe PMC text mining. Sharing a sentence is not in itself a finding about the gene and the disease.
RIMBP3B shares sentences with these, for which no sentence is quoted: ovarian carcinoma (1 paper).